SMN2 (survival of motor neuron 2, centromeric)
Diseases named in the same sentence as SMN2 in open-access papers (continued):
Sharing a sentence is not in itself a finding about the gene and the disease.
neurodegenerative disease (4 papers, 2012 to 2020). A disorder of the central nervous system characterized by gradual and progressive loss of neural tissue and neurologic function. "Different hnRNP Q isoforms have been associated with differential splicing activity of the SMN2 exon 7 in the neurodegenerative disease SMA." (PMID 32748079, 2020). "This review will discuss how SMN1 and SMN2 CNVs are detected and why accurate measurement of SMN1 and SMN2 copy numbers is relevant for SMA and other neurodegenerative diseases." (PMID 27014701, 2016).
myopathy (2 papers, 2022 to 2023). A disease of the muscle in which the muscle fibers do not function properly. "Second, examinations of mutants that derived residual muscle SMN from two SMN2 copies hinted at a role for this protein in satellite cells, implying that myopathy in SMA must originate, at least in part, in these progenitors." (PMID 37737261, 2023). "Notably, we also found that 20% more myogenesis- and myopathy-related genes were dysregulated in the more vulnerable triceps muscles of Smn−/−;SMN2 mice compared to the resistant quadriceps muscles." (PMID 35902978, 2022). "Unsurprisingly, we observed a larger number of significantly dysregulated myopathy and myogenesis genes in triceps of Smn−/−;SMN2 mice than in the more resistant quadriceps, some of which overlapped with the subset of genes aberrantly expressed in Fn14−/− mice and Tweak−/− mice." (PMID 35902978, 2022).
SMN2 also shares sentences with these, for which no sentence is quoted: Alzheimer disease (2 papers); acute respiratory failure (1); amyloidosis (1); Anxiety (1); Areflexia (1); bone tumors (1); cancer (1); chronic myelomonocytic leukemia (1); colorectal cancer (1); depression (1); fibromuscular dysplasia (1); fragile X-associated tremor/ataxia syndrome (1); generalized epilepsy (1); Holt-Oram syndrome (1); Huntington disease (1); Hyporeflexia (1); keratoconus (1); Lynch syndrome (1); macular degeneration (1); muscular disorder (1); Onset (1); osteoarthritis (1); paraplegia (1); Parkinson disease (1); Pelizaeus-Merzbacher disease (1); Prader-Willi syndrome (1); retinopathy (1); Rett syndrome (1); Skeletal muscle atrophy (1); spinal muscular atrophy type II (1).
A further 4 diseases each share a sentence with SMN2 in 1 paper.